NTRK1 (neurotrophic receptor tyrosine kinase 1)
Diseases named in the same sentence as NTRK1 in open-access papers (continued):
Sharing a sentence is not in itself a finding about the gene and the disease.
colorectal cancer (47 papers, 2011 to 2025). A primary or metastatic malignant neoplasm that affects the colon or rectum. "In colorectal cancer patients, chromosomal rearrangements involving the NTRK1 gene (encoding the TRKA protein) are shown in a small subset of patients and are associated with the constitutive activation of the kinase domain of TRKA." (PMID 29617282, 2018). "Given the rapidity, broad applicability and low costs of IHC in clinical diagnostic labs, we investigated the prevalence of NTRK1 rearrangements in gastrointestinal and colorectal cancers with TrkA IHC." (PMID 26472021, 2015). "In other reports, NTRK1 rearrangements in metastatic gastrointestinal cancer, colorectal cancer, glioblastoma, and non-small cell lung cancer patients were observed." (PMID 38635549, 2024). "NTRK1 G595R, NTRK1 G667C, and NTRK3 G623R kinase domain mutations have been reported in colorectal cancer and mammary analog secretory carcinoma (MASC)." (PMID 39590120, 2024). "NTRK1 was initially identified as a fusion oncogene in colorectal cancer in 1986, known as trk A (tropomyosin receptor kinase)." (PMID 39166093, 2024). "Previous studies have identified that there is a chimeric oncogene involving the tropomyosin 3 (TPM3) gene and a specific genomic locus of NTRK1 in colorectal cancer (CRC) patients." (PMID 39590120, 2024). "Of the 17 NTRK+ colorectal cancer identified, 14 cases had NTRK1‐rearranged events with TPM3 being the most frequent fusion partner, and the remaining three cases were NTRK3+ fusion cases." (PMID 35506567, 2022). "Among them, a total of 17 NTRK+ colorectal cancer patients were identified, including 14 cases of NTRK1+ CRCs and three cases of NTRK3+ CRCs." (PMID 35506567, 2022). "In colorectal cancer patients, chromosomal rearrangements involving NTRK1 gene (encoding the TRKA protein) are shown in a small subset of patients and are associated with the constitutive activation of the kinase domain of TRKA." (PMID 28903424, 2017). "In this study, the incidence of TrkA (encoded by NTRK1) IHC positivity is 1.5% in gastric cancer and 2.7% in colorectal cancer patients by IHC." (PMID 26472021, 2015). "For example, NTRK1/2/3 fusion genes have also been reported as being significantly more frequently found in microsatellite instability (MSI)-high cancers in the context of colorectal carcinoma patients." (PMID 32466202, 2020). "In addition, DS-6051b effectively induced tumor shrinkage of the KM12 xenograft, the colorectal cancer cell with NTRK1 rearrangement." (PMID 31399568, 2019). "The use of multi-gene panels such as F1LCDx enables identification of other alterations within colorectal cancer (e.g., KRAS) or across tumor types (e.g., NTRK1/2/3) which are relevant to diagnosis and potential treatment options for patients." (PMID 40832988, 2025). "The overall prevalence of RTK fusions in colorectal cancers was 1.0%, with the top frequent fusion genes being RET (0.34%), ALK (0.19%), and NTRK1 (0.10%)." (PMID 36369474, 2022). "MET, NTRK1, and PPARG showed outlier expression in samples from three patients with GEJ adenocarcinoma, colorectal cancer, and urothelial cancer, respectively." (PMID 34385467, 2021).
thyroid cancer (47 papers, 2003 to 2025). "In addition, NTRK3 or NTRK1 fusion genes are associated with distant metastasis in thyroid carcinomas." (PMID 35572973, 2022). "Only five patients with thyroid carcinoma were included in an integrated analysis of three ongoing early-phase trials in metastatic or locally advanced solid tumors harboring oncogenic NTRK1, NTRK2, and NTRK3 gene fusions treated with entrectinib." (PMID 40061140, 2025). "Most TPM3::NTRK1 gene fusions (n = 12) were found in thyroid cancer (n = 5, 41.7%), then STS (n = 3, 25.0%)." (PMID 38925616, 2024). "Thyroid cancers harboring genetic rearrangements involving NTRK1/3 (~2% of PTC) can respond to treatment with TRK inhibitors, including FDA-approved larotrectinib and entrectinib." (PMID 36909304, 2023). "This analysis revealed that seven of the novel identified variants were located in genes previously associated with thyroid cancer: MSH6, FOXM1, EPCAM, HOOK3, BMP1, TG and NTRK1." (PMID 37175550, 2023). "Alternative analysis of the DEGs using GSEA obtained a top ranked list of six enriched pathways including two annotated pathways that include NTRK1, namely 'Neuroactive_Ligand_Receptor_Interaction' and “Thyroid Cancer'." (PMID 33456567, 2021). "Subsequent studies demonstrated that RET, TRK or NTRK1 were frequently translocated in a fraction of thyroid carcinomas, as well as other epithelial and soft tissue neoplasms." (PMID 26943776, 2016). "Dysregulation of NTRK1, BRAF, Ras, and PAX/PPARγ has also been associated with the development and progression of other thyroid cancers." (PMID 22630170, 2012). "In several different cancers, TPR is present through fusion genes, which is formed by coiled-coil motif in TPR with some kinase partner genes such as MET (gastric cancer), NTRK1 (thyroid carcinoma), FGFR1 (myeloproliferative syndromes), and ALK (lung adenocarcinoma)." (PMID 34722501, 2021). "Relevant molecular alterations encountered in thyroid cancer progression comprise gene rearrangements of tyrosine kinase receptors, such as the RET/PTC and NTRK1, activating point mutations of the RAS and BRAF genes, and the oncogenic fusion protein PAX8-PPARγ." (PMID 25807528, 2015). "The results showed that mast cells with high expression of NTRK1 were activated in the following pathways: neural tyrosine signal pathway, butyric acid metabolism, endocytosis, apoptosis, lysine degradation, hematopoietic system lineage, thyroid cancer, and olfactory conduction." (PMID 34912722, 2021). "Proteomic studies on PTC tissue from humans have suggested NTRK1, metalloproteinases (MMP-1, MMP-9 and MMP-13) and Cathepsins (-W and -X), NF-KB and other apoptosis associated proteins as radiation-induced PTC biomarkers, together with SPANXA as an important protein for thyroid cancer development." (PMID 33382739, 2020). "Evaluation of thyroid FNAs with the Unified Assay identified all fusion proteins described for thyroid cancer in TCGA, the most common fusion pair being PAX8-PPARg, with other common fusion partners including RET, NTRK1/3, ALK, and BRAF." (PMID 36675685, 2022). "Kinase fusions have been identified in distinct histological subtypes of thyroid cancer, including papillary thyroid cancer (PTC; RET, NTRK1/2/3), medullary thyroid cancer (ALK), and poorly differentiated thyroid cancer (RET, ALK)." (PMID 32292131, 2020). "Oncogenic TrkA fusion products potentiate NGF-dependent carcinogenesis in CRC, thyroid cancer, and AML, leading to the concept of NTRK1 functioning as an oncogene." (PMID 31812953, 2019). "NTRK1 (neurotrophic receptor tyrosine kinase 1) also fuses to TPM3; seen in more than 5% of thyroid cancers, the event again connects the TPM3 5′ end with the NTRK1 kinase domain." (PMID 30836651, 2019). "Of note similar to RET, rearrangement of NTRK1 has been described in thyroid cancer (TPM3-NTRK1, TPR-NTRK1, TFG-NTRK1)." (PMID 24744988, 2014).
thyroid cancer (continued). "In thyroid carcinomas, the proto-oncogenes RET and NTRK1 are often found to be activated through chromosomal rearrangements." (PMID 22096618, 2011). "Mutations in BRAF, RET/PTC, NTRK1, or RAS have been reported in up to 70% of differentiated thyroid cancers and historically it does not depend on an MMR deficiency." (PMID 39062638, 2024). "In thyroid cancer, TPM3::NTRK1 (n = 5) was the most frequently detected fusion gene." (PMID 38925616, 2024). "Translocated promoter region (TPR) with NTRK1 was found in thyroid cancer, and sequestosome 1 (SQSTM1)-NTRK1 fusion in STS and non-small cell lung cancer (NSCLC)." (PMID 38144536, 2023). "Notably, thyroid cancers have the highest frequency of recurrent kinase fusions (63/498, 13%), and all fusion events including ALK, BRAF, MET, NTRK1, NTRK2, RAF1 and RET are mutually exclusive in this cancer type." (PMID 25204415, 2014). "Tumor cells derived from one of the two TrkA IHC+ CRC patients were sensitive to a potent pan-TrkA inhibitor, entrectinib, with inhibition of downstream pathways, suggesting that NTRK1 rearrangements in non-lung or non-thyroid cancer can be a potent actionable genetic aberration as in NSCLC." (PMID 26472021, 2015).
anhidrosis (39 papers, 2009 to 2025). Lack of sweating or the ability to sweat when provoked by the appropriate stimulus. "Congenital insensitivity to pain with anhidrosis is caused by a mutation in the neurotrophic receptor tyrosine kinase 1 gene (NRTK1)." (PMID 39789590, 2025). "Congenital Insensitivity to Pain with Anhidrosis (CIPA) is a rare hereditary neuropathy caused by NTRK1 gene mutations, predisposing patients to recurrent infections and chronic wounds." (PMID 39455857, 2025). "For example, it is known that human NTRK1 gene that encodes trkA is responsible for congenital insensitivity to pain with anhidrosis (CIPA), an autosomal recessive disorder characterized by a lack of pain sensation and anhidrosis." (PMID 39194496, 2024). "Congenital insensitivity to pain with anhidrosis (CIPA) is a rare autosomal recessive disorder because of NTRK1 gene mutations, leading to an inability to perceive pain and temperature and lack of sweating." (PMID 39687654, 2024). "Congenital insensitivity to pain with anhidrosis (CIPA) is an extremely rare autosomal recessive disorder caused by loss‐of‐function mutations of the NTRK1 gene, affecting the autonomic and sensory nervous system." (PMID 38581121, 2024). "CIPA is specifically designated as HSAN type 4, where NTRK1 mutations lead to the loss of pain and temperature sensation, anhidrosis, recurrent fever, joint deformities, and intellectual disability." (PMID 38581121, 2024). "We report a case of congenital insensitivity to pain with anhidrosis (CIPA) with a novel neurotrophic tyrosine kinase receptor type 1 (NTRK1) gene mutation." (PMID 36160132, 2022). "Reanalysis of WES data revealed a variant, c.287 + 7 G > T in intron 2 of NTRK1 [NC_000001.10 (NM_002529.3)] confirming the diagnosis of congenital insensitivity to pain with anhidrosis (MIM# 256800) in III-2." (PMID 34276053, 2021). "De novo mutations in the GNB1 gene have been associated with cutaneous mastocytosis and neurodevelopmental delays, while mutations in the NTRK1 gene were found to cause anhidrosis and palmar hyperkeratosis." (PMID 31569353, 2019). "Patient 15 had moderate cognitive delay and self-mutilation behaviour secondary to congenital insensitivity to pain with anhidrosis due to a homozygous mutation in NTRK1." (PMID 31081514, 2019). "We report here a case of compound heterozygosis for two novel NTRK1 splice site mutations in a 6 year old patient with autosomal recessive congenital insensitivity to pain with anhidrosis (CIPA)." (PMID 21708027, 2011). "The literature states that the NTRK1 variant typically manifests with anhidrosis, the propensity to develop corneal ulcers that heal poorly, intellectual disability in the majority of patients, predisposition to staph aureus infections, Charcot joints, and dry skin with or without lichenification." (PMID 39403642, 2024). "Of the novel missense variants, only one missense variant in NTRK1 could be classified as likely pathogenic, due to the pathognomonic phenotype with insensitivity to pain and anhidrosis." (PMID 32214227, 2020). "Ntrk1-null mice suffer from severe sensory and sympathetic neuropathies and loss-of-function NTRK1 mutations are identified in paediatric patients with congenital insensitivity to pain and anhidrosis." (PMID 31738426, 2019). "The secondary symptoms associated with the respective genes differ between SCN9A (anosmia) and NTRK1 (anhidrosis)." (PMID 39156962, 2024). "Hereditary sensory and autonomic neuropathy type 4 (HSAN4), also known as congenital insensitivity to pain with anhidrosis (CIPA), is a rare genetic disorder caused by NTRK1 gene mutations, affecting nerve growth factor signaling." (PMID 38133079, 2023). "CIP with Anhidrosis (CIPA) is the most common type of CIP, which is caused mainly by mutations in NTRK1 and NGF genes, and is characterized by mental retardation and the inability to sweat (Anhidrosis)." (PMID 37248554, 2023).
anhidrosis (continued). "For example, mutations in the neurotrophic tyrosine kinase receptor type 1 gene (NTRK1) and nerve growth factor-β (NGFB) result in CIP with an anhidrosis phenotype." (PMID 25309764, 2014). "HSAN IV [also called congenital insensitivity to pain with anhidrosis (CIPA)] presents with a severe sensory neuropathy, anhidrosis, and mental retardation and is due to mutations in the NTRK1 gene." (PMID 20142852, 2009). "CIPA is caused by mutations in the NTRK1 gene, resulting in a lack of pain perception and anhidrosis." (PMID 38581121, 2024). "Hereditary sensory and autonomic neuropathy type 4 (HSAN4), or congenital insensitivity to pain with anhidrosis (CIPA), is a rare autosomal recessive disorder caused by mutations in the NTRK1 gene, resulting in pain insensitivity, anhidrosis, and temperature dysregulation." (PMID 38058353, 2023). "Whereas CIP/HSAN-related pathogenic SCN9A variants frequently lead to anosmia as a secondary symptom, NTRK1-related neuropathy is accompanied by lack of sweat gland innervation with anhidrosis and sometimes life-threatening hyperthermia." (PMID 37769650, 2023). "The third exception is a mutation present in all the Israeli Arab Bedouins p.P615Sfs*12 in the NTRK1 gene causing congenital insensitivity to pain with anhidrosis but has not been reported in other populations and therefore probably occurred more recently." (PMID 28302154, 2017). "For instance, HSAN typeIV, also known as Congenital Insensitivity to Pain with Anhidrosis (CIPA), is caused bymutations in the nerve growth factor (NGF) receptor (TrkA/NTRK1), and HSAN type V iscaused by mutations in NGF that either prevent its processing, secretion, or downstreamsignaling." (PMID 27561110, 2016). "HSAN V is similar, though without the mental retardation or significant anhidrosis, and has been shown to result from mutations in NTRK1 and also NGFB." (PMID 20142852, 2009). "Characterized by an inability to perceive pain and temperature, along with a lack of sweating (anhidrosis), CIPA is caused by mutations in the NTRK1 gene." (PMID 39687654, 2024). "Our study identified two mutations in NTRK1 gene in Palestinian CIPA unrelated families, and a novel mutation in SCN9A gene that causes CIP without Anhidrosis." (PMID 37248554, 2023).
colon carcinoma (36 papers, 2014 to 2025). "In line with this evidence, we have shown that HGF, which can be produced by tumor‐associated fibroblasts, induced entrectinib resistance in NTRK1 rearranged colon cancer and ROS1 rearranged NSCLC models." (PMID 36416133, 2023). "A recent study showed G667C mutation-expressing entrectinib-resistant brain-metastatic colon cancer of cells responded to another NTRK1 inhibitor foretinib." (PMID 29617282, 2018). "Among the NTRK genes, NTRK1 was initially recognized as an actionable oncogene in colon cancer by Mariano Barbacid and colleagues in 1982." (PMID 38397049, 2024). "Tropomyosin receptor kinase (TRK) fusion is one of the oncogenic driver causes of colon cancer, and tropomyosin 3-neurotrophic receptor tyrosine kinase 1 (TPM3-NTRK1) fusion has been detected in the KM12SM cell line." (PMID 34659525, 2021). "We then further investigated NTRK1 fusions because NTRK1, which encodes for membrane-bound TrkA protein, has been shown to be rearranged with TPM3 in colon carcinoma and papillary thyroid carcinoma." (PMID 26716414, 2016). "Clinicopathological analysis demonstrated that the proportion of patients with NTRK1 fusion-driven TrkA expression was substantial in Korean and Chinese patients with colon cancer, accompanied with poor overall survival." (PMID 26716414, 2016). "Whereas the oncogenicity of NTRK1 fusions was well characterized in papillary thyroid carcinoma and lung adenocarcinoma, it remains to be elucidated in colon cancer." (PMID 26716414, 2016). "It suggests that NTRK1 fusion has the potential prognostic and predictive significance in colon cancer." (PMID 26716414, 2016). "Although we performed the clinical follow-up of the patients, most of the patients were diagnosed after 2010 and it is too soon to determine any clinicopathological effects of the NTRK1 fusions in colon cancer." (PMID 26716414, 2016). "NTRK1 fusions were mutually exclusive oncogenic drivers of colon cancer that were accompanied with in vitro potential of colony formation and in vivo tumorigenicity comparable to KM12, a human colon cancer cell line harboring TPM3-NTRK1 fusion." (PMID 26716414, 2016). "NTRK1 fusions were mutually exclusive colon cancer drivers with tumorigenicity in cells and in animals." (PMID 26716414, 2016). "The clinical relevance of NTRK1 fusion was assessed with independent cohorts that were comprised of 216 Korean and 472 Chinese patients with colon cancer." (PMID 26716414, 2016). "Using high-throughput 3-dimensional culture system, the IC50 was 0.089 uM for entrectinib in NTRK1 rearranged colon cancer PDCs." (PMID 26472021, 2015). "NTRK1 was initially identified as an oncogene in 1982 by Mariano Barbacid and colleagues during gene transfer assays aimed at discovering genes with transforming capabilities in human tumor specimens, specifically those from colon cancer." (PMID 38397049, 2024). "We investigated whether growth factors that can be produced by the microenvironment affect sensitivity of NTRK1‐rearranged colon cancer KM12SM cells and ROS1‐rearranged NSCLC HCC78 cells to entrectinib both in vitro and in vivo." (PMID 36416133, 2023). "Therefore, the negative selection of somatic variants was preceded and revealed the mutually exclusive oncogenicity of NTRK1 fusions in colon cancer." (PMID 26716414, 2016). "Therefore it is useful to use KM12 for high throughput screening of drug candidates for NTRK1 fusion-positive colon cancer treatment." (PMID 26716414, 2016). "Taken together, these results demonstrated that the use of TrkA kinase-specific inhibitors may provide a new therapeutic strategy for targeted treatment not only for NTRK1 fusion-driven lung adenocarcinoma and sarcoma but also for colon cancer." (PMID 26716414, 2016). "Taken together, these results imply that NTRK1 fusion could be a clinically relevant target for the therapeutic intervention of colon cancer." (PMID 26716414, 2016).
colon carcinoma (continued). "In addition, METex14del occurs exclusively to ALK, ROS1, NTRK1, NTRK3 or RET fusions indicating METex14del is likely a driver mutation and defines a unique molecular subset of gastric and colon cancers." (PMID 26375439, 2015). "In addition, an NTRK1 fusion was identified in a colon cancer patient." (PMID 34385467, 2021). "Furthermore, the prevalence and the clinical relevance of NTRK1 fusions remain largely unknown in colon cancer." (PMID 26716414, 2016). "Therefore, we anticipate that immunohistochemistry accompanied with FISH could be used for the prognosis of colon cancer-harboring NTRK1 fusion." (PMID 26716414, 2016). "Therefore, NTRK1 fusion was granted as a therapeutic target to treat colon cancer." (PMID 26716414, 2016). "The first NTRK1 gene fusion was identified in a colon cancer specimen, which had sequences from the TPM3 (non-muscle tropomyosin) gene." (PMID 26472021, 2015).